UGT1A7 (UDP glucuronosyltransferase family 1 member A7)
Description:
[Isoform 1]: UDP-glucuronosyltransferase (UGT) that catalyzes phase II biotransformation reactions in which lipophilic substrates are conjugated with glucuronic acid to increase the metabolite's water solubility, thereby facilitating excretion into either the urine or bile. Essential for the elimination and detoxification of drugs, xenobiotics and endogenous compounds. Catalyzes the glucuronidation of endogenous estrogen hormone epiestradiol. Involved in the glucuronidation of F2-isoprostane (5-epi-5-F2t-IsoP). Involved in the glucuronidation of the phytochemical ferulic acid at the carboxylic acid group. Also catalyzes the glucuronidation of the isoflavones genistein, daidzein, glycitein, formononetin, biochanin A and prunetin, which are phytoestrogens with anticancer and cardiovascular properties. Involved in the glucuronidation of the AGTR1 angiotensin receptor antagonist caderastan, a drug which can inhibit the effect of angiotensin II. Involved in the biotransformation of 7-ethyl-10-hydroxycamptothecin (SN-38), the pharmacologically active metabolite of the anticancer drug irinotecan. Also metabolizes mycophenolate, an immunosuppressive agent. [Isoform 2]: Lacks UGT glucuronidation activity but acts as a negative regulator of isoform 1.
Synonyms: UDPGT 1-7; UGT1-07; UGT1.7; UGT-1G; UGT1G
Tractability: Small molecule: a high-quality ligand is known. Antibody: UniProt predicts a signal peptide or a membrane-spanning region. PROTAC: its protein half-life has been measured.
Target class: Enzyme; Transferase
Safety:
Unwanted effects reported when the protein is acted on. In parentheses: how it was acted on, where the effect was seen, and who reports it.
adverse drug reactions (source: ClinPGx)
adverse reactions (source: ClinPGx)
better response (source: ClinPGx)
cardiotoxicity (source: ClinPGx)
hand-foot syndrome (source: ClinPGx)
hyperbilirubinemia (source: ClinPGx)
hyperprolactinemia (source: ClinPGx)
liver failure (source: ClinPGx)
nephrolithiasis (source: ClinPGx)
neutropenia (source: ClinPGx)
severe neutropenia (source: ClinPGx)
vomiting (source: ClinPGx)
worse response (source: ClinPGx)
Gene: Protein-coding gene on chromosome 2 (233,681,901 to 233,773,300, forward strand). Ensembl gene ENSG00000244122.
Subcellular location: Endoplasmic reticulum membrane
Pathways (Reactome):
Drug ADME: Aspirin ADME
Metabolism: Glucuronidation
Gene Ontology:
Molecular function: enzyme binding; enzyme inhibitor activity; glucuronosyltransferase activity; protein homodimerization activity; protein kinase C binding; retinoic acid binding; protein heterodimerization activity; UDP-glycosyltransferase activity
Biological process: estrogen metabolic process; flavonoid metabolic process; toxin catabolic process; xenobiotic catabolic process; xenobiotic metabolic process; cellular response to glucocorticoid stimulus; coumarin metabolic process; flavone metabolic process; liver development; retinoic acid metabolic process; monocarboxylic acid metabolic process
Cellular component: endoplasmic reticulum; endoplasmic reticulum membrane
Genetic constraint (gnomAD): Loss-of-function variants: 33 observed, 46.38 expected, observed/expected ratio (o/e) 0.71, 90% interval 0.54 to 0.95. The upper end of that interval is the gene's LOEUF score, 0.95, which puts it in group 4 of 6, group 1 being the genes least tolerant of losing a copy. Missense variants: 684 observed, 694.24 expected, observed/expected ratio (o/e) 0.99, 90% interval 0.93 to 1.05. Synonymous variants: 274 observed, 263.5 expected, observed/expected ratio (o/e) 1.04, 90% interval 0.94 to 1.15.
Homologues: Orthologues: mouse Ugt1a9 (79% identical), dog UGT1A6 (79% identical), mouse Ugt1a10 (79% identical), mouse Ugt1a8 (78% identical), mouse Ugt1a7c (78% identical), zebrafish ugt2a7 (40% identical), zebrafish ugt2b5 (38% identical), zebrafish ugt2b1 (38% identical), zebrafish si:ch73-334d15.1 (38% identical), zebrafish ugt5g1 (36% identical), zebrafish ugt5c1 (36% identical), zebrafish ugt5a2 (36% identical), and 98 more. Paralogues in human: UGT1A8 (95% identical), UGT1A10 (94% identical), UGT1A9 (93% identical), UGT1A6 (68% identical), UGT1A5 (68% identical), UGT1A3 (68% identical), UGT1A4 (67% identical), UGT1A1 (67% identical), UGT2B10 (44% identical), UGT2B17 (44% identical), UGT2B4 (43% identical), UGT2B11 (43% identical), and 9 more.